CD8A (CD8 subunit alpha)
Diseases named in the same sentence as CD8A in open-access papers (continued):
Sharing a sentence is not in itself a finding about the gene and the disease.
tumor (continued). "CD8α+CD4- DCs play a key role in anti-tumor immunity due to their ability to cross-present tumor antigen to CD8+ T cells." (PMID 25886502, 2015). "It is likely that the declining proportions of cross-presenting CD8α+CD4- DCs and the presence of disabled and inappropriately activated lipid-laden tumor-associated DCs that migrated to dLNs account for this observation." (PMID 25886502, 2015). "Mouse T cell surface marker CD3 epsilon chain (CD3e) and CD8 alpha chain (CD8a) were chosen as test criteria for tumor-infiltrating lymphocytes, while IFNγRβ, CCR2, IL-2Rα and CCR5 were chosen as Th1-associated markers." (PMID 26417929, 2015). "Given the ability of these subsets to cross-present antigens, CD8α+ and CD103+ DCs are traditionally associated with the cross-priming of pathogens- and tumor-derived antigens to CD8+ T cells." (PMID 26539197, 2015). "It has been demonstrated that these factors can affect the infiltration of CD8α-positive T-cells in tumors and affect the type of the macrophage response (pro-tumor, M2, or anti-tumor, M1)." (PMID 26374556, 2015). "Batf3−/− mice are selectively deficient of the antigen cross-presenting CD8α+ and CD103+DC subsets, which are required for in vivo priming of tumor-specific CD8+ T cells." (PMID 25941586, 2014). "We examined the infiltration of CD4+/CD8a+ T cells into tumor tissues after administration of SART3/CD40L+GM-CSF gene-loaded polyplex micelles by immunohistochemical analysis." (PMID 25013909, 2014). "Depletion of CD4+ or CD8a+ T cells by neutralizing antibodies deteriorated the anti-tumor efficacy of the DNA vaccine." (PMID 25013909, 2014). "CD8α+DCs are critical for cross-presentation of tumor and viral antigens because of their well-specialized cross-presentation capacity and their superior ability to prime antitumor CTL responses without enhancing GVHD." (PMID 24600454, 2014). "In our DNA vaccine system, CTLs are a major effector that inhibits tumor progression, because the survival benefit was completely abrogated by in vivo CD8a+ cell depletion." (PMID 25013909, 2014). "Recently, Fuertes Marraco and colleagues established murine dendritic cell lines from splenic CD8α tumor cDCs, which are similar to normal splenic cDCs." (PMID 23626840, 2013). "Tumors can also subvert immunity by regulating pDC production of IFN-α, a type I IFN that functions as a “signal 3” cytokine for CD8+ T cell activation and that promotes the survival and Ag retention of CD8α+ DC that cross-prime tumor-specific CD8+ T cells." (PMID 23874338, 2013). "Two different groups have recently reported the in vivo relevance of endogenous IFN-I signaling on CD8α DC for promoting CD8+ T-cell-dependent spontaneous tumor rejection." (PMID 24400008, 2013). "Administration of poly(I:C), a TLR3 agonist, as a tumor vaccine adjuvant was shown to selectively upregulate PD-L1 expression on mouse CD8α+ DCs." (PMID 24348481, 2013). "Of note, type I IFN have been shown to provide strong signal for CD8α+ DCs promoting CD8+ T cell cross-priming in vivo against antigens derived from dying tumor cells." (PMID 23616948, 2013). "Similar results were obtained using tumor cells killed by the chemotherapeutic agent cyclophosphamide as a source of antigenic material for CD8α DC." (PMID 24400008, 2013). "In a murine model of melanoma, only CD8α+ DCs isolated from TDLNs were able to cross-present the secreted tumor antigen, ovalbumin (OVA)." (PMID 20976125, 2010). "In contrast, we have recently shown that both CD8α+ and CD8α− TDLN DCs were able to cross-present the membrane tumor antigen, hemagglutinin (HA)." (PMID 20976125, 2010). "Co-administration of PC61 either on day 15 or day 24, however, completely blocked the Ad-Flt3L and Ad-TK dependent increase in total numbers of tumor infiltrating immune cells (p>0.05), and CD8a+ T cells (p>0.05)." (PMID 18431473, 2008).
tumor (continued). "For immune checkpoint inhibitors, a pre‐existing inflamed tumor microenvironment, characterized by high CD8+ tumor‐infiltrating lymphocytes and inflammatory gene signatures (e.g., CD8A, CD274, LAG3), correlates with improved survival with nivolumab and atezolizumab plus bevacizumab." (PMID 41509174, 2026). "Here, immunophenotype is determined by CD8a IHC staining of FFPE tumor sections." (PMID 40501795, 2025). "CD8A-targeting peptides enhance T-cell tumor response, acting as immunoregulators." (PMID 40809316, 2025). "Moreover, in the CSS-low tumor microenvironment, CD8A expression on T cells was substantially elevated, and the HLA-A/B/C-E-CD8A interaction emerged as the most pronounced ligand-receptor axis." (PMID 40777020, 2025). "Moreover, while the CD28 transmembrane portion (TM) is commonly used in CARs, CD8α TM or hinge regions have also proven advantageous in CARs against tumor antigens, and in our lab, against SARS-CoV-2 antigens." (PMID 40867541, 2025). "CD8A showed a scattered yet discernible presence in the peripheral tumor areas." (PMID 40547013, 2025). "While tumor cells with high antigen density elicited the activation of HER2 CAR T cells with a conventional 45 amino acid CD8α hinge as well as the 34 amino acid truncated hinge, tumor cells with low antigen density selectively activated the longer hinge bearing CAR." (PMID 41221288, 2025). "The enhanced infiltration of CD8α+ T cells into the tumor microenvironment in Rab27a/b-deficient mice does not mitigate tumor progression or increase animal survival relative to tumor-bearing controls (WT and dHET)." (PMID 40408475, 2025). "Furthermore, according to IHC staining results, we observed a significant increase in the expression of CD86 (an M1 macrophage marker) and CD8 (a CTL marker) in the tumour tissue of the combination treatment group." (PMID 40830825, 2025). "Additionally, the results from the multiple immunofluorescence analysis of NUAK1, CD8α, and GZMB demonstrated that the overexpression of NUAK1 markedly decreased the population of GZMB+ CD8+ T cells within the tumor microenvironment." (PMID 39901136, 2025). "Notably, the combined therapeutic effect was eliminated when the GL261 GBM tumor–bearing mice were depleted of CD8+ T cells (45.5 days in oeTRAF3 + PD-L1 mAb mice vs. 37 days in oeTRAF3 + PD-L1 mAb + CD8α mAb mice)." (PMID 39932808, 2025). "Idecabtagene is comprised of a murine extracellular scFv of the C11D5.3 monoclonal antibody that binds to BCMA on tumor cells followed by a human CD8α hinge and transmembrane domain fused to the costimulatory molecule 4–1BB (CD137) and the T cell activation domain CD3ζ chain." (PMID 40061940, 2025). "Notably, the combined therapy led to the most substantial increase in CD8a+ T cell infiltration, further enhancing the anti-tumor immune response." (PMID 40873559, 2025). "At 5 days post-IR, the CD45 + immune infiltrate further expanded; however, the density of intact CD8a + TILs began to decline, possibly due to exhaustion or apoptosis triggered by the immunosuppressive tumor microenvironment, including increased PD-L1 expression." (PMID 39941761, 2025). "For instance, CD8A is essential for cytotoxic T-cell-mediated anti-tumor immunity, and its overexpression may indicate alterations in immune surveillance." (PMID 40227503, 2025). "Tocilizumab may control cytokine release syndrome in the context of immunotherapy.JBH492 may affect the biological behavior of SKCM cells or the tumor microenvironment by targeting and regulating genes such as CD8A and LSP1." (PMID 40547036, 2025). "The killing effects of drug combinations were compromised when utilizing anti-CD8α antibody to deplete CD8+ T cells in immune intact mice, suggesting drug combinations treatment induces the generation and expansion of cytotoxic CD8+ T cells, which are responsible for the inhibition of tumor growth." (PMID 41281743, 2025).
tumor (continued). "To exclude the possibility that the increased influx of CD8α+ T cells into the tumor microenvironment of dKO mice was due to increased CD8α+ T cell numbers in the circulation, we conducted fluorescence-activated cell sorting (FACS) analysis on their content in peripheral blood." (PMID 40408475, 2025). "This trend was consistent when the tumor tissues were stratified by CD8A or CD8B expression." (PMID 39679910, 2025). "The study results showed that the CD8, CD8α+, and DC numbers, mainly responsible for antigen phagocytosis and cross-presentation, significantly increased in the combination-treated mice with tumor-draining lymph nodes (TDLN)." (PMID 40486836, 2025). "In contrast, the anti-tumor effect of this combination disappeared with the addition of an inhibitor of CD8a or in T-cell immune-deficient Rag-/- mice, suggesting that SFRT enhances the efficacy of immune checkpoint inhibitors via CD8+ T lymphocytes." (PMID 40666094, 2025). "Specifically, CD8A could be overexpressed in tumor samples due to increased T-cell activity; its expression could imply that the immune system is mounting a stronger response to the aggressive GS 10 cancer." (PMID 40227503, 2025). "We administered anti-CD8α or isotype antibodies to WT and uPA–/– tumor-bearing mice." (PMID 40959092, 2025). "Since CD8a+ T cells play a key role in directly killing pathogen-infected cells and tumor cells, XBS02 may have greater potential in eliminating infected cells and inhibiting the replication and spread of pathogens in the body." (PMID 41295528, 2025). "Moreover, due to the vital function of CD8+ T cells in anti‐tumour immunity, we explored the prognostic value of GSN in patients with high or low CD8+ T cell infiltrations (separated by CD8A expressions) in the TCGA‐KIRC cohort." (PMID 40375605, 2025). "Moreover, gene set enrichment analysis (GSEA) and CD8A+ detection noted that RFA exerts antitumor effects directly on tumor cell death and possibly on TME remodeling." (PMID 39871325, 2025). "We found that the expression of CD11c and CD8a was markedly greater in the GW9662-treated tumor tissues than in control tumor tissues, and the quantity of cDCs and CD8+ T cells was notably greater in the GW9662-treated tumor tissues than in the control tissues." (PMID 38786003, 2024). "Notably, mice treated with CD8α– or CD8α+ NK cells had similar tumor control initially (days 1 and 4), and differences between the groups became more apparent at later time points (days 7–15)." (PMID 38805302, 2024). "Given that K562 cells lack HLA class I expression, we next sought to determine whether CD8α– NK cells had enhanced responses against the HLA-expressing tumor cell lines Jeko-1 and HL60." (PMID 38805302, 2024). "We next evaluated the relationship between baseline CD8 infiltration (assessed by the mRNA expression level of CD8A), pretreatment tumor CD274 (PD-1 ligand 1) and KDR mRNA expression levels, and the T cell-inflamed gene expression profile of 15 biomarkers and the response to treatment." (PMID 38584166, 2024). "However, elevated CD8A expression is associated with a high TMB, with genes involved in the immune checkpoint, and with the presence of several types of tumor-infiltrating immune cells." (PMID 38396726, 2024). "Analysis of bulk tumor gene expression data from TCGA revealed a significant negative correlation between the genes encoding OTUB2 and intratumoral T-cell abundance (CD3E and CD8A) in multiple cancer types." (PMID 38167274, 2024). "The association between pretreatment tumor inflammation and the efficacy of BEMPEG + NIVO versus NIVO was evaluated using a four-gene signature, comprised of the following genes: CD274 (PD-L1), CD8A, LAG3, and STAT117 (see “Methods”)." (PMID 39025948, 2024). "Our data showed that B2M expression was strongly associated with CD8A expression in the multiple probes (0.9<R<0.93) not in the tumor cells, but in cancer str of the CRC tumors." (PMID 38557819, 2024).
tumor (continued). "Given the critical role of CD8+ T cells in immune-mediated tumor rejection and as a prognosis factor in many solid tumors, we next determined, using RT-qPCR analysis, the levels of SERPINE1 and CD8A, a cell surface receptor found on cytotoxic T lymphocytes, in 20 surgical COAD specimens." (PMID 38448406, 2024). "Moreover, the results of IHC staining showed that the protein level of Pdl1 was significantly higher while that of Cd8α was significantly lower in tumor tissues of Pdl1-overexpred group, and vice versa." (PMID 39421264, 2024). "Finally, while K562s lack HLA expression, it is also possible that some level of tonic inhibition is tumor-target independent and is mediated by NK-NK interactions of CD8α/KIR-HLA." (PMID 38805302, 2024). "Current research predominantly attributes the cross-presentation of tumor antigens to CD8α+ DCs." (PMID 38512518, 2024). "Future studies further assessing the anti-tumor function of CD8α iNKT cells would be of interest." (PMID 39170618, 2024). "Moreover, the expression of the critical downstream mediator of IRE1α pathway, XBP1, was also highly associated with the mRNA levels of the indicators of lymphocytes and anti-tumor immunity, including PTPRC (encoding CD45), CD8A, GZMB and IFNG." (PMID 38291473, 2024). "Utilizing CellChat, we uncovered a nuanced interaction between macrophage-expressed HLA-B and T-cell-harbored CD8A within the tumor microenvironment, which may be crucial for shaping immunotherapeutic strategies and enhancing immunosurveillance mechanisms." (PMID 39081317, 2024). "The mouse CD8α+ Clec9a+ DCs (or stem-DCs) produced in this study demonstrated antitumor effects characterized not only by a reduced volume of ascites and number of tumor implants but also high levels of immunostimulatory cells and cytokines and low levels of immunosuppressive cytokines." (PMID 36596856, 2023). "Hence, in our study we reported a novel role of DVL2 in oncogenic Wnt and EGFR signaling modulation as well as its promising correlation with markers of tumor immune regulation (such as TILs and cytotoxic CD8α)." (PMID 36809986, 2023). "Immune-related genes, such as CD8A, CD8B, GZMA, GZMB, and PRF1, that may indicate the function of tumor-infiltrating CD8 + T cells were considerably enriched in the group receiving combination therapy." (PMID 37777634, 2023). "Moreover, further investigation showed that pentamidine boosted the immune response to tumor growth by increasing the population of CD8a+ T cells and decreasing Treg abundance, thus prolonging the survival of tumor-bearing mice." (PMID 37205112, 2023). "An exploratory biomarker analysis included a four-gene gene expression signature (CD8A, STAT1, LAG3, and CD27), TMB (tumor mutation burden), and the pulmonary immune prognostic index (LIPI) measured according to LDH levels and neutrophil/lymphocyte ratios (NLR) in peripheral blood." (PMID 38136333, 2023). "Given the substantial effect of CAR T-vax treatment on cytotoxic effector gene expression in endogenous CD8+ T cells, we evaluated the importance of endogenous CD8+ T cells in tumor control, by comparing CAR T-vax treatment in WT versus CD8α−/− tumor-bearing mice." (PMID 37413990, 2023). "Therefore, the association between Teffs and IPS was investigated by characterizing Teffs in the tumor nest versus the stroma using CD8A and GZMB." (PMID 36998102, 2023). "Clinical analysis reveals a positive correlation between LOXL4 expression in CD68+ cells and PD-L1 levels in human HCC tissue, while high LOXL4 expression in CD68+ cells and low CD8A expression in tumor tissue serve as predictive markers for poor survival in HCC patients." (PMID 37626849, 2023). "All these pro‐tumour genes were correlated with the expression of Cd8a and Rara." (PMID 37997519, 2023). "High CD8A expression represented a high proportion of CD8+ CTLs in the tumor microenvironment." (PMID 37064155, 2023).
tumor (continued). "Immunohistochemistry (IHC) staining was used for the detection of CD8α in tumor tissues." (PMID 37853469, 2023). "Furthermore, we performed immunostaining for CD163, a human macrophage marker, and for CD8α, a cytotoxic T cells marker, and the number of intra-tumor positive cells was analyzed." (PMID 36809261, 2023). "For adoptive T cell therapy, higher abundance of the Bacteroidales S24-7 family is correlated with higher IL-12 and more CD8α+ DCs in the peripheral blood of mouse model, suggesting that this species could improve anti-tumor immunity." (PMID 37520576, 2023). "Patients with high expression of CD8A in the tumor site exhibited a higher overall survival rate." (PMID 35145233, 2022). "Besides these scores, the XP genes, immune-specific single genes (CD8A, CXCL9, CD274, and CXCL13) and tumor mutational burden (TMB) were cross-correlated." (PMID 35174087, 2022). "Nonetheless, the lack of research into the role of CD8A in tumor microenvironment predisposes to limitations in its clinical utilization." (PMID 36035168, 2022). "Despite being expressed in various immune cell types, CTLs present a predominant expression level of CD8A, which could be a direct indication of pre-existing antitumor immunity with tumor-infiltrating CTLs in TME." (PMID 36035168, 2022). "Moreover, in contrast to the near-complete tumor regression achieved in the CPA + control IgG group, an extended period of tumor growth stasis followed by robust tumor regrowth was evident in mice receiving CPA + anti-CD8α antibody." (PMID 36187936, 2022). "We then used a CD8α-depleting antibody to remove CD8α+ cDC1s in vivo and then determine pan-DC function in their absence ex vivo in the context of alloreactive T-cell stimulation and tumor-killing." (PMID 35980974, 2022). "In addition, a recent study revealed that CD8A was positively correlated with the immune score in almost all 33 tumor types." (PMID 35572597, 2022). "Their results indicated that the sugar capsules, which were composed of mannan (Mann-capsule) carrying messenger RNA (mRNA), promoted strong activation of DC and antigen presentation, and further induced powerful antigen-specific CD4 and CD8α T cell responses with anti-tumor efficacy in vivo." (PMID 35664731, 2022). "However, anti-PD-L1 treatment resulted in upregulation or downregulation of numerous genes in CD45+ tumor-infiltrating immune cells in TCh3 tumors, including Cd3d, Cd3e, Cd3g, Cd8a, Cd8b1, Nkg7, Ccl5, Ets1, Icos, Cxcr6, Pdcd1, Lag3, Prf1, and Gzmb (right)." (PMID 35366939, 2022). "Next, the sorted CD11b+F4/80+ TAM from B16-F10 tumors were exposed to either OVA or BSA (control) soluble proteins and were analyzed for their ability to cross-present Ag and subsequently activate naive CD8a+ T cells isolated from tumor-free OT-I transgenic mice." (PMID 35503656, 2022). "Among cDCs, cDC1 (CD8α+ DCs) are considered as bystanders which integrate signals derived from intracellular infection to tailor the appropriate CD4+ T-cell response along with anti-tumor CD8+ T-cell activation with the help of their unique property of cross presentation." (PMID 36238311, 2022). "Lower tumor purity might indicate a higher proportion of stromal area and/or higher density of tumor-infiltrating immune cells, which was partially suggested by the lower CD8A methylation in clusters 4–6 which might reflect higher infiltration of CD8+ T cells." (PMID 35130881, 2022). "CD8α, produced from CD8A, is a canonical marker for the T cell population involved in tumour surveillance and forms a heterodimer with CD8β, or may homodimerise; CD8A is the only gene exclusive to T-net that correlates with nivolumab response in MEL_PROG." (PMID 35743743, 2022). "Subsequently, we analyzed SQLE expression and its association with biomarkers of MHC (B2M, HLA-B, HLA-C, TAP1, and TAP2), dendritic cells (BATF3), macrophages (CD68 and IL1A), type-I anti-tumor responses (CD8A and GZMB), and cell proliferation (MKI67) in 178 PAAD tissues." (PMID 35720314, 2022).